TTN (titin)
Diseases named in the same sentence as TTN in open-access papers (continued):
Sharing a sentence is not in itself a finding about the gene and the disease.
cardiomyopathy (continued). "In 8 (66.7%), we found de novo variants in known cardiomyopathy genes (TTN, DSP, SCN5A, TNNC1, TPM1, CRYAB, MYH7)." (PMID 32013205, 2020). "There are numerous point mutations of TTN leading to missense changes in single amino acids that are associated with diverse phenotypes including several types of cardiomyopathies." (PMID 32859027, 2020). "While still in its infancy and currently plagued by the issue of immaturity, it provides exciting approaches to study the role of titin variants in cardiomyopathies and we are looking forward to future developments in the field." (PMID 31147888, 2019). "Six years after the proband's initial presentation, a 204‐gene combined neuromuscular and cardiomyopathy panel from a second commercial laboratory identified a partial deletion of TTN (exons 346‐362), interpreted as likely pathogenic." (PMID 31489791, 2019). "Mutations of RBM20 gene are known to cause cardiomyopathies because RBM20 regulates circular RNA production from the Titin (TTN) gene." (PMID 31092860, 2019). "Given the scarcity of human cardiac tissue for research purposes, especially from healthy control individuals, it is not surprising that only few studies have looked at molecular changes in the hearts of cardiomyopathy patients carrying titin variants." (PMID 31147888, 2019). "This review will discuss the contribution of variants in titin to inherited cardiac conditions (cardiomyopathies) and how model systems, such as animals and cellular systems, can help to provide insights into underlying disease mechanisms." (PMID 31147888, 2019). "Genetic mutations associated with cardiomyopathy play a key role in disease formation, especially the mutation of sarcomere encoding genes and ATP kinase genes, such as titin, lamin A/C, myosin heavy chain 7, and troponin T1." (PMID 30995779, 2019). "TTN gene encodes titin, the largest protein of the human genome [305 kilobases (kb)] a protein involved in many cardiomyopathies." (PMID 29181379, 2017). "RBM20, a member of the SRSF family, regulates the splicing of many genes that are linked to cardiomyopathy, including titin." (PMID 27914791, 2017). "The aim of this review is to discuss the challenges in diagnosing the correlation between TTN mutations and the different types of cardiomyopathy in the clinical setting." (PMID 27493940, 2016). "Mutations in titin have been associated with cardiomyopathy and skeletal myopathy (reviewed in Chauveau et al27)." (PMID 27625337, 2016). "This review discusses the current knowledge of TTN genetic variations in cardiomyopathies and the impact of the diagnosis of TTN pathogenic mutations in the clinical setting." (PMID 27493940, 2016). "In this work, atomic resolution three-dimensional structures of the affected titin region were generated as well as, to our knowledge, the first mouse model of a cardiomyopathy-associated titin mSNP." (PMID 27683155, 2016). "It furthermore highlights that rare titin missense variants, currently often ignored or left uninterpreted, should be considered to be relevant for cardiomyopathies and can be identified by the approach presented here." (PMID 27625337, 2016). "Evidence accumulated over the past two decades has identified titin as a main coordinator of cardiac muscle homeostasis, and its dysfunction through genetic mutation as an important factor in cardiomyopathy." (PMID 27683155, 2016). "Targeted next-generation sequencing demonstrated that mutations in cardiomyopathy-related genes, especially in TTN, are common in families with both PPCM and DCM." (PMID 25896781, 2015). "While the mutations associated with the development of cardiomyopathies affect several domains throughout the M-band portion of titin, the ones that are linked to skeletal myopathies are mainly contained within the last Ig domain of titin, MIg10." (PMID 25961035, 2015).
cardiomyopathy (continued). "The majority of cardiomyopathy causing candidate genes encode structural proteins among which titin probably is the most important one." (PMID 24531746, 2014). "Mechanisms underlying TTNtv-associated cardiomyopathy may include haploinsufficiency and aggregate formation due to impaired ubiquitin-mediated degradation; the amyloidogenic potential of titin has also been described." (PMID 41440877, 2025). "Notably, structural genes such as TTN are often linked to cardiomyopathies and have also been associated with arrhythmic phenotypes, suggesting a notable connection between structural and electrical heart diseases." (PMID 41465321, 2025). "The discovery of a rare TTN missense variant that co-segregates with restrictive cardiomyopathy (RCM) strongly suggests that TTN may represent a novel causative gene in this severe cardiomyopathy." (PMID 41190030, 2025). "Such mutations have been proposed to modify titin-based passive stiffness and may lead to cardiomyopathy." (PMID 39677424, 2025). "They further suggest that pharmacological targeting of Class II HDACs may represent a therapeutic strategy for mitigating TTN deficiency-related gene dysregulation in cardiomyopathy." (PMID 41283336, 2025). "Mutations in the TTN gene are speculated to bring about cardiomyopathies through disruption in sarcomere assembly or contractility, or triggering aberrant splicing." (PMID 38438525, 2024). "The roles of Gal-3 and titin in cardiac-related MYBPC3 gene mutations may provide further insights into the roles of these biomarkers in the pathophysiology of cardiomyopathies." (PMID 39619937, 2024). "Many titin mutations are linked to cardiomyopathies and neuromuscular diseases." (PMID 37178278, 2023). "The recent association of MVP with pathogenic variants in several known cardiomyopathy genes, such as TTN (titin) and FLNC (filamin C) could explain disproportionate LV remodeling." (PMID 35498019, 2022). "Cytoskeletal protein variants include variants in desmin, lamin A/C, titin, myosin heavy and light chain, junctophilin, nucleoporin, nesprin, and filamin C. These cytoskeletal protein variants have a strong association with the development of cardiomyopathy." (PMID 35159226, 2022). "Further investigations of titin biomechanics may contribute to developing more potent targeted therapies for titin-associated cardiomyopathies." (PMID 36147537, 2022). "This yield increased to 3.41% with the expanded ACMG SF v3.0 list, identifying an additional 71 individuals, most of whom are protein-truncating variant carriers in the newly included cardiomyopathy gene TTN (53/71) and hereditary breast and ovarian cancer (HBOC) syndrome gene PALB2 (11/71)." (PMID 36335097, 2022). "In a small case series of 25 patients with early-onset AF (<45 years, without significant comorbidities) referred to a tertiary care centre, 21 had at least one rare variant in a cardiomyopathy-associated gene (4 with TTN LOF and 1 with RMB20 which is implicated in titin splicing)." (PMID 33982075, 2021). "Furthermore, a recent study has identified telethonin as a target of the proteasome in a titin missense variant mouse model of cardiomyopathy, where degradation of unbound, cytoplasmic telethonin by the proteasome results in proteasomal overload." (PMID 34566695, 2021). "As the second-longest gene in humans, genetic variation in TTN is common, and it may be challenging to differentiate benign polymorphisms from true cardiomyopathy-causing mutations." (PMID 33467574, 2021). "The muscle phenotype in patients with titin mutations is strongly dependent on the mutational burden, for example homozygous deletions of the C-terminus of titin will lead to early onset myopathy with death due to cardiomyopathy." (PMID 30738787, 2020). "We will review how mutations in TTN contribute to cardiomyopathy." (PMID 32859027, 2020).
cardiomyopathy (continued). "The cardiomyopathy associated gene CMYA5 (myospryn) that binds to the C-terminus of titin was also shown to interact with PKA, however, currently it is not well understood, which role PKA exactly plays in the response to mechanical and humoral stress in the M-band." (PMID 30738787, 2020). "It will also give an outlook onto exciting technological developments, such as in the field of CRISPR, which may facilitate future research on titin variants and their contributions to cardiomyopathies." (PMID 31147888, 2019). "Moreover, a body of evidence in human patients and animal models has shown that changes of the ratios of these two TTN isoforms are associated with cardiomyopathies and heart failure." (PMID 29438341, 2018). "Compared to the conventional Sanger sequencing, NGS allows the coverage of a much wider panel of genes including giant genes such as titin, and enables the expansion of analysis to genes associated with cardiac arrhythmias, neuromuscular disorders, and cardiomyopathy phenocopies." (PMID 27662471, 2016). "Functional data generated from biophysical and protein-binding experiments on this titin missense variant provide further support of a causative role in cardiomyopathy through domain misfolding and destabilization, resulting in impaired binding to the ligand telethonin (also known as t-cap)." (PMID 27625337, 2016). "Nevertheless, there is some interesting evidence that TTN missense mutations may have a modifier role leading to a greater severity of cardiomyopathy." (PMID 27493940, 2016). "This system has been applied to the study of cardiomyopathies caused by titin truncating mutations and perhaps might be applicable to the study of titin mSNPs." (PMID 27683155, 2016). "Hence, titin missense variants are currently often ignored or left uninterpreted when found in cardiomyopathy patients." (PMID 27625337, 2016). "In addition to cardiomyopathies, mutations in the TTN gene also cause muscular phenotypes, and the two conditions may coexist." (PMID 39063061, 2024). "Moreover, it is plausible that TTN mutations may trigger aberrant splicing occurrences, leading to the production of deficient or abnormal Titin isoforms, thus playing a role in the pathogenesis of cardiomyopathy c." (PMID 38438525, 2024). "In addition, individual TTN missense variants have been associated with cardiomyopathies, but due to the giant size of titin and the high abundance of missense variants in normal cohorts, it is challenging to evaluate variants identified in an individual by genetic testing." (PMID 36935760, 2023). "Dominant variants in TTN may underlie a proportion of skeletal myopathy disorders which currently remain genetically uncharacterized and should be considered in the differential diagnosis of patients with skeletal muscle weakness and cardiomyopathy." (PMID 32815318, 2020). "The present study’s genetic analysis revealed the presence of rare TTNtv-s in the constitutively expressed exons in all titin bands in the patients with cardiomyopathy." (PMID 40022161, 2025). "Previously, we reported a patient with a mixed cardiomyopathy phenotype carrying an extended deletion in TTN, for which bioinformatic modeling showed unfolding of protein motifs and the formation of amyloid-like structures." (PMID 41440877, 2025). "The GWAS of NT-proBNP levels identified cardiomyopathy- or heart failure-associated genetic loci (eg, HSPB7/CLCNKA, CDKN1A, TTN, FLNC, and BAG3)." (PMID 41054850, 2025). "The titin gene (TTN), which encodes the giant sarcomeric protein titin, is increasingly recognized as a key genetic determinant in various cardiomyopathies." (PMID 41283336, 2025). "Among HTx recipients, a pathogenic mutation in the RBM20 gene was identified in one patient, while two others carried VUS in TTN and PKP2, which are genes associated with cardiomyopathies." (PMID 40126245, 2025).
cardiomyopathy (continued). "Our findings demonstrate that alterations in TTN expression are associated with various forms of cardiomyopathy, including DCM, HCM, and PPCM, characterized by a notable downregulation of TTN expression in DCM patients." (PMID 41283336, 2025). "Building on this rationale, in this study, we examine TTN expression across cardiomyopathies (DCM, HCM, PPCM), with a focus on its downregulation in DCM patients." (PMID 41283336, 2025). "The purpose of this review is to provide a comprehensive understanding of the critical role TTN mutations play in DCM and other forms of cardiomyopathy." (PMID 41190030, 2025). "What is the association of TTN and BAG3 with late-onset cancer therapy–related cardiomyopathy (CCM) among childhood cancer survivors?" (PMID 40540274, 2025). "In the fifth patient, we detected pathogenic biallelic variants in the TTN gene that are associated with Salih myopathy (Salih congenital myopathy (congenital myopathy 5 with cardiomyopathy; CMYP5; OMIM: 611705))." (PMID 39519277, 2024). "Notable genes such as titin (TTN), Bcl2-associated athanogene 3 (BAG3), and lamin A/C (LMNA) are implicated in PPCM, revealing a complex genetic landscape similar to other cardiomyopathies." (PMID 39118717, 2024). "Genetic profiling reveals a complex landscape with key genes like titin (TTN), Bcl2-associated athanogene 3 (BAG3), and lamin A/C (LMNA) implicated in PPCM, suggesting genetic predispositions and shared pathways with other cardiomyopathies." (PMID 39118717, 2024). "In the present study, we evaluated their interaction with Titin and consider their interaction with Titin in the pathogenesis of cardiomyopathies." (PMID 38438525, 2024). "We describe the recent understanding of the functional impact of titin variants and highlight FHOD3 as a novel cardiomyopathy-associated gene." (PMID 38771459, 2024). "Titin (TTN) is the most common gene implicated in DCM, representing 15–20% of DCM cases, followed by Lamin A/C (LMNA) cardiomyopathy at 6%." (PMID 38277082, 2024). "For instance, pathogenic variants and rare variants in TTN and MYH7 genes have been reported in patients with chemotherapy-induced cardiomyopathy." (PMID 38202009, 2023). "By cardiomyopathy subtype, MYH7 deleterious variants clustered within myosin head and neck regions and TTN truncating variants clustered within the A-band zone in male and female patients." (PMID 37477868, 2023). "There was an excess burden of splice-disrupting variants in PKP2 (5.9%), FLNC (2.7%), TTN (2.8%), MYBPC3 (8.2%) and MYH7 (1.3%), in distinct cardiomyopathy subtypes, and KCNQ1 (3.6%) in long QT syndrome." (PMID 37821546, 2023). "Titin biophysical properties have fundamental importance in cardiac functions, and mutations in the titin gene (TTN) are recognized causes of cardiomyopathies such as dilated cardiomyopathy and hypertrophic cardiomyopathy." (PMID 36147537, 2022). "It is well conceived that RBM20 cardiomyopathy is provoked by titin isoform switching in combination with resting Ca2+ leaking." (PMID 34523260, 2021). "Despite these limitations and caveats, our A178D mice represent a valuable tool to study titin-related cardiomyopathy." (PMID 33637999, 2021). "TTN, GAA, LAMA2, and MYBPC3 contained the most variants in the three subgroups which confirm the impact of these genes in the complex pathogenesis of cardiomyopathies and VT." (PMID 33552729, 2021). "TTN, GAA, LAMA2 and MYBPC3 harbored the most variants in the three subgroups which confirm the high impact of these genes in complex pathogenesis of cardiomyopathies and VT demonstrated in previous studies." (PMID 33552729, 2021). "Subsequent to these initial investigations, the giant sarcomeric protein-coding gene TTN emerged as a key gene in cardiomyopathy, accounting for up to 25% of familial DCM cases." (PMID 33467574, 2021).
cardiomyopathy (continued). "Post-translational modifications of titin by phosphorylation of the spring-like I-band are capable of changing the length and stiffness of titin and are correlated with cardiomyopathy." (PMID 32859027, 2020). "We reidentified all five loci harboring Mendelian cardiomyopathy-linked genes found in prior common variant analyses of DCM (ALPK3, BAG3, FLNC, PLEKHM2, and TTN)." (PMID 32382064, 2020). "Together, these data suggest that the RBM20 cardiomyopathy phenotype is more severe and arrhythmogenic, and cannot be solely explained by changes in titin." (PMID 32789749, 2020). "For the remaining MYH7 HCM samples, variants in the following other cardiomyopathy genes were also found: DSP, MHY6, NEBL, PSEN1, RBM20, and TTN." (PMID 32344918, 2020). "Data analysis also indicated that there are many genes related to cardiomyopathy, such as TTN, NEFH, PLEC, CASQ2, and SYNE1." (PMID 33200202, 2020). "This suggests that changes in alternative splicing of elastic proteins such as myomesin and titin contribute to a cardiomyopathy phenotype, especially in the case of dilated cardiomyopathy." (PMID 30738787, 2020). "In 6 of 10 cases of sporadic DCM and in single cases of RCM and HCM, we found de novo mutations in genes previously associated with cardiomyopathy (CRYAB, DSP, MYH7, SCN5A, TNNC1, and TTN)." (PMID 32013205, 2020). "A few lncRNAs are located in the introns of cardiomyopathy-related genes (e.g., TTN, ACTC1, TPM1, JPH2, ANKRD1, DTNA, TMPO, and FHL2) or physically close to these genes." (PMID 32344918, 2020). "The detailed mechanism of TTN-directed mechanotransduction signaling was investigated in recent cardiomyopathy studies." (PMID 30995779, 2019). "The addition of the TTN gene to the cardiomyopathy panel in 2015 only resulted in an increase of class 4 and 5 variants in the DCM patients, but not in other cardiomyopathy patients." (PMID 30847666, 2019). "We further confirmed the ITGB6 (Integrin Subunit Beta 6) and TTN (Titin) genes among the several genes showing selection signals in the three cardiomyopathy pathways." (PMID 31440273, 2019). "A recent study found that approximately one-half of the patients with NCCM had a mutation in a cardiomyopathy gene, and mutations in the MYH7, MYBPC3, and TTN genes were the most prevalent." (PMID 30809538, 2019). "In recent years, the mechanisms for how TTN and potential modifier genes contribute to cardiomyopathy have been more clearly elucidated." (PMID 31849696, 2019). "A previously published report of rare variants in TTN in over 1,126 SCD victims, composed of patients with channelopathies, cardiomyopathies, and SUDS, identified 554 potentially causative variants." (PMID 28704380, 2017). "A complex network of endocrine, neuroendocrine, paracrine, and autocrine signaling modulates the activity of TTN in the pathophysiology of cardiomyopathy." (PMID 28510119, 2017). "DCM hearts expressed longer TTN isoforms, which is known to cause disease in RBM20-mediated cardiomyopathy." (PMID 28903782, 2017). "Considering rare variants for each cardiomyopathy type, in ARVC patients, the highest number of rare variants was found in TTN and RYR2 genes (4 variants) followed by OBSCN and PKP2 (3 variants)." (PMID 28750076, 2017). "The genetic screening of the TTN gene, now pursued in large patient populations, has the potential to assist the diagnosis of cardiomyopathies, assess prognosis and guide therapy." (PMID 27683155, 2016). "Although if it is only one of the genes involved in cardiomyopathies, the titin gene (TTN) deserves a separate discussion due to its peculiarities." (PMID 27617263, 2016). "The aim of this review is to understand the clinical role of TTN mutations in DCM and in other cardiomyopathies." (PMID 27493940, 2016). "Among the genes involved in cardiomyopathies, TTN plays a central role because of its frequency and the key structural, mechanical, and regulatory role within the sarcomere in the striated muscle." (PMID 27493940, 2016).